GATA1 (GATA binding protein 1)
Description:
Transcriptional activator or repressor which serves as a general switch factor for erythroid development. It binds to DNA sites with the consensus sequence 5'-[AT]GATA[AG]-3' within regulatory regions of globin genes and of other genes expressed in erythroid cells. Activates the transcription of genes involved in erythroid differentiation of K562 erythroleukemia cells, including HBB, HBG1/2, ALAS2 and HMBS.
Synonyms: GATA-1; GF-1; ERYF1; GF1; NFE1; NF-E1; CNSHA9; HAEADA; XLANP; XLTDA; XLTT
Tractability: PROTAC: UniProt records ubiquitination sites on it.
Gene: Protein-coding gene on chromosome X (48,786,540 to 48,794,311, forward strand). Ensembl gene ENSG00000102145.
Subcellular location: Nucleus
Subcellular location (Human Protein Atlas): Nucleoplasm
Pathways (Reactome):
Gene expression (Transcription): RUNX1 regulates genes involved in megakaryocyte differentiation and platelet function; RUNX1 regulates transcription of genes involved in differentiation of HSCs
Hemostasis: Factors involved in megakaryocyte development and platelet production
Gene Ontology:
Molecular function: C2H2 zinc finger domain binding; chromatin DNA binding; DNA binding; DNA-binding transcription activator activity, RNA polymerase II-specific; DNA-binding transcription factor activity; protein binding; RNA polymerase II cis-regulatory region sequence-specific DNA binding; RNA polymerase II transcription regulatory region sequence-specific DNA binding; RNA polymerase II-specific DNA-binding transcription factor binding; sequence-specific DNA binding; sequence-specific double-stranded DNA binding; transcription cis-regulatory region binding; transcription coregulator binding; DNA-binding transcription factor activity, RNA polymerase II-specific; chromatin binding; cis-regulatory region sequence-specific DNA binding; transcription coactivator binding; zinc ion binding
Biological process: basophil differentiation; eosinophil differentiation; eosinophil fate commitment; erythrocyte development; erythrocyte differentiation; male gonad development; megakaryocyte differentiation; negative regulation of apoptotic process; negative regulation of extrinsic apoptotic signaling pathway in absence of ligand; negative regulation of transcription by RNA polymerase II; platelet aggregation; platelet formation; positive regulation of DNA-templated transcription; positive regulation of erythrocyte differentiation; positive regulation of transcription by RNA polymerase II; regulation of definitive erythrocyte differentiation; regulation of glycoprotein biosynthetic process; cell fate commitment; anatomical structure morphogenesis; animal organ regeneration; cell differentiation; cellular response to cAMP; cellular response to follicle-stimulating hormone stimulus; cellular response to lipopolysaccharide; positive regulation of cytosolic calcium ion concentration; and 5 more
Cellular component: nucleoplasm; nucleus; protein-DNA complex; transcription regulator complex; transcription repressor complex; chromatin
Gene-disease validity (ClinGen):
ClinGen rates the evidence that GATA1 causes each of these diseases.
GATA1-Related X-Linked Cytopenia (X-linked): Definitive. X-Linked cytopenia characterized by anemia and/or thrombocytopenia.
Cancer hallmarks: invasion and metastasis (promotes); proliferative signalling (promotes); angiogenesis (promotes); escaping programmed cell death (promotes)
Homologues: Orthologues: chimpanzee GATA1 (99% identical), macaque GATA1 (98% identical), rabbit GATA1 (95% identical), dog GATA1 (95% identical), pig GATA1 (94% identical), guinea pig GATA1 (90% identical), rat Gata1 (86% identical), mouse Gata1 (86% identical), tropical clawed frog gata1 (45% identical), zebrafish gata1a (41% identical), Drosophila melanogaster grn (35% identical), Drosophila melanogaster srp (27% identical), and 3 more. Paralogues in human: GATA2 (40% identical), GATA3 (38% identical), GATA6 (31% identical), GATA4 (31% identical), GATA5 (30% identical), TRPS1 (23% identical), ZGLP1 (8% identical).
Diseases named in the same sentence as GATA1 in open-access papers:
GATA1 is named in the same sentence as 176 diseases in open-access papers, as found by Europe PMC text mining. Sharing a sentence is not in itself a finding about the gene and the disease. The quoted sentences say what the papers report.
anemia (62 papers, 2009 to 2026). A reduction in the number of red blood cells, the amount of hemoglobin, and/or the volume of packed red blood cells. "Specifically, the targeted deletion of Gata1 causes early embryonic lethality around embryonic days 10.5-11.5 from severe anemia, due to erythroid differentiation arresting at the proerythroblast stage." (PMID 40048486, 2025). "For instance, missense mutations in GATA1 cause anemia and thrombocytopenia, highlighting its essential role in hematopoiesis." (PMID 40650116, 2025). "Loss of Gata1 results in embryonic lethality between e10.5–e11.5 due to anemia, as other studies have shown Gata1 null primitive and definitive erythroblasts undergo apoptosis." (PMID 38790192, 2024). "The knockout of GATA1 in mice showed embryonic lethality caused by severe anemia, which indicates that GATA1 is an essential factor for the development and maturation of hematopoietic lineage cells." (PMID 38784708, 2024). "RNH1 knock-out mice were reported to die from anemia caused by failed erythroid cell maturation due to deficient translation of the transcription factor GATA1." (PMID 36935417, 2023). "Mutations in GATA1, or GATA1-target sequences, cause anemia, which can be accompanied by thrombocytopenia, consistent with its role both megakaryopoiesis and erythropoiesis." (PMID 35330735, 2022). "The use of these technologies are likely to increase the detection of these types of pathologic variants and provide further insights into the role of GATA1, and other transcription factors, in inherited anemias." (PMID 35330735, 2022). "The intronic GATA1 mutation was identified in two male patients sharing the same pedigree that included multiple cases with anaemia." (PMID 35846220, 2022). "Germline defects in the transcription factor GATA1 are known to cause dyserythropoiesis with(out) anemia and variable abnormalities in platelet count and function." (PMID 36231035, 2022). "The phenotype of mice carrying the Gata1low mutation that decreases expression of Gata1 in erythroid cells and megakaryocytes, includes anemia, thrombocytopenia, hematopoietic failure in bone marrow and development of extramedullary hematopoiesis in spleen." (PMID 34707640, 2021). "The loss of Gata1 expression leads to erythroid maturation arrest and embryonic lethality due to anemia." (PMID 28910278, 2017). "The critical role of these TFs in defining erythroid cell state is highlighted by human genetic studies that have identified causal mutations for various forms of anemia in GATA1 and KLF1." (PMID 25521328, 2014). "Mutations that completely block erythropoiesis, such as Gata-1 or Fog-1 null mutations cause visible anaemia in the liver and circulation by E12.5 and are lethal between E12.5– E15.5." (PMID 23469164, 2013). "It is hypothesized that the mechanism underlying anaemia related to zinc deficiency involves impaired functionality of the zinc finger protein GATA-1, crucial for the differentiation and proliferation of erythroblasts." (PMID 40344157, 2025). "Intronic mutations affecting GATA1 splicing occur in rare pediatric anemias." (PMID 40424086, 2025). "Because the zinc finger transcription factor GATA-1 is essential for both primitive and definitive erythropoiesis, zinc deficiency could cause anemia." (PMID 39221327, 2024). "On the other hand, the exchange of arginine with tryptophane, instead of glutamine, as in the R216W GATA1 variant, has been described in a patient affected by anemia, splenomegaly, painful photosensitive bullous dermatosis, and hirsutism, a condition also known as congenital erythropoietic purpura." (PMID 36291092, 2022). "Therefore, Gata1 deficient mice die of severe anemia between day 10.5 and 11.5 of gestation with sign of intraembryonic hemorrhage." (PMID 34707640, 2021). "Deficiencies of GATA1 can cause thrombocytopenia and anemia." (PMID 30065722, 2018).
anemia (continued). "Splice site mutations of GATA1 have beenfound in a family with macrocytic anaemia and in patients with Diamond-Blackfan anaemia(an anaemia characterised by a selective hypoplasia of erythroid cells), resulting inimpaired production of the full-length form of the GATA1 protein (Refs 19, 20)." (PMID 26953528, 2016). "Our study eliminates transcriptional effects on p27, GATA1 or NF-E2 as underlying causes for anaemia but as Fbxo7 is a multi-functional E3 ubiquitin ligase, we cannot eliminate the possibility that it may also act via p27-independent mechanisms." (PMID 26095538, 2015). "Bidirectional Effects on Erythropoiesis: While ASXL1 truncations repress erythroid differentiation via GATA1/KLF1 silencing (contributing to anemia), concomitant H3K27me3 loss at proliferative loci (e.g., HOXA9) may paradoxically expand early erythroid progenitors." (PMID 40772034, 2025). "GATA1 germline mutations may lead to GATA1-related cytopenia in males, which is characterized by thrombocytopenia and/or anemia ranging from mild to severe, and one or more of the following: platelet dysfunction, mild β-thalassemia, neutropenia, and congenital erythropoietic porphyria." (PMID 37627314, 2023). "Loss of HLTF leads to reduced GATA1 expression, impaired RBC maturation, anemia, and compensatory extramedullary hematopoiesis." (PMID 41521666, 2026). "The knockout of the Zfpm1 gene, coding for FOG-1, results in early embryonic lethality due to anemia in mice, similar to the embryonic lethal phenotype of the Gata1 gene knockout." (PMID 40048486, 2025). "Our study indicates that GDF11-mediated SMAD2 activation results in an increase in functionally impaired GATA1 isoforms, consequently contributing to anemia and influencing responses to luspatercept in MDS." (PMID 40424086, 2025). "Expression of the GATA1 short isoform (GATA1s) in a mouse model led to anemia, which was rescued by the murine version of luspatercept, RAP-536 (human ActRIIB fused with murine Fc)." (PMID 40424086, 2025). "Degradation of GATA1 downstream of NLRP3 inflammasome activation has been proposed as a mechanism leading to anemia in MDS37." (PMID 41298546, 2025). "Similar to the Gata1 knockout phenotype, deletion of the Zfpm1 gene in mice resulted in embryonic lethality between embryonic days 10.5 to 12.5, due to severe anemia." (PMID 40048486, 2025). "This seems to suggest that if the increased expression of ARID1B had an ameliorating effect on space anaemia while in-flight in this case, this was likely achieved through pathways other than GATA1-mediated differentiation and erythroid maturation." (PMID 38862545, 2024). "Mutations of GATA1 that impair its ability to interact with the co-repressor FOG1 (Friend of GATA1) also lead to variable degrees of thrombocytopenia and anemia.." (PMID 35330735, 2022). "The co-inheritance of a GATA1 G208R with an ALAS2 R479Q led to a shift of the GATA1-typical anemia towards a sideroblastic anemia with macrothrombocytopenia." (PMID 36231035, 2022). "Consistently, low levels of the EpoR regulator Gata1 result in embryonic anemia but normal adult erythropoiesis." (PMID 33566111, 2021). "Gata1 is on the X chromosome: male mice expressing 5% of the protein (Gata1.05 strain) die around day E12.5 because of anemia, as Gata1 null mutants do, whereas Gata1.05 females frequently develop erythroblastic leukemias." (PMID 34359655, 2021). "Myeloma cell infiltration causes elevated expression of CCL3 in BM, which suppresses the erythropoiesis of HSPCs and results in anaemia by downregulating the level of GATA1 in HSPCs." (PMID 33239656, 2020). "Gata1 knockout mice die between embryonic day 10.5 and 11.5 because of anaemia, as erythroid differentiation is blocked at the pro-erythroblast stage." (PMID 30653565, 2019). "The notion that low levels of GATA1 lead to the development of myelofibrosis comes from studies in the GATA1-low mouse model, that also develops anemia with age." (PMID 30809156, 2019).
anemia (continued). "Although glucocorticoid is not involved in erythropoiesis under steady state conditions, it inhibits GATA-1 expression when stress erythropoiesis is induced by a severe decrement of erythrocytes consequent to anaemia and other conditions." (PMID 31114014, 2019). "Gata1 knockout in mice results in embryonic lethality around E10.5–E11.5 due to severe anemia, with GATA1-null cells undergoing massive apoptosis at the proerythroblastic stage." (PMID 30809156, 2019). "Requirement of functional GATA1 for haematopoiesis is also observed in several humandiseases, such as anaemia, leukaemia and thrombocytopenia." (PMID 26953528, 2016). "Gata1 knockout mice die around day E10.5 of gestation due to severe anemia and conditional ablation of Gata1 has shown its requirement in the erythro-megakaryocytic lineages in adult mice." (PMID 27152938, 2016). "Since Gata1 knockout mice are lethal due to severe anemia, different Gata1 targeted mouse models were generated to investigate the role of Gata1 in adult mice, including ΔneoΔHS and Gata1.05 mice." (PMID 27152938, 2016). "We propose that the CID-dependent dimerization system combined with the EpoR intracellular domain and the Gata1 gene regulatory region generates a novel peroral strategy for the treatment of anemia." (PMID 25790231, 2015). "The physiological role of this new pathway is evidenced by transgenic mouse experiments with GATA-1 mutants unable to bind pRb/E2F, which result in embryonic lethality by anemia." (PMID 19513100, 2009). "In a family of patients with an inherited mutation of the GATA-1 gene that results in GATA-1s expression, a severe anemia occurs." (PMID 19513100, 2009). "The cofactor Friend-of-GATA-1 (FOG-1) binds to GATA-1 and modulates its activity on given target genes, and mice deficient in either GATA-1 or FOG-1 die from severe anemia." (PMID 19513100, 2009). "Additionally, CCL3 enhances MM-mediated anemia by suppressing erythropoiesis through GATA1 downregulation." (PMID 38690165, 2024). "This activation also results in degradation of the erythroid transcription factor GATA1, through caspase-1 activation, changing the ratio between GATA1 and the myeloid transcription factor PU.1 favoring myeloid commitment, maturation arrest, and anemia." (PMID 36835307, 2023). "In mouse models, the knockdown of Gata1 leads to maturation arrest at the proerythroblast stage, thrombocytopenia and the increased proliferation of megakaryocytes, whereas Gata1-null mice are embryonically lethal due to severe anemia." (PMID 35328001, 2022). "Mechanistically, caspase-1 degraded the master erythroid transcription factor, GATA binding protein 1, provoking anemia and myeloid lineage bias that was reversed by cGAS inhibition in vitro and in Tet2–/– hematopoietic stem and progenitor cell–transplanted mice." (PMID 35788117, 2022). "In the C-terminal GATA1 zinc finger (aa258–282), which mainly mediates the DNA-binding activity of GATA1, only one pathogenic variant has been detected so far (L268M), causing a bleeding phenotype due to a severe platelet defect but no anemia." (PMID 36231035, 2022). "Gata1 knock-out in mice leads to embryonic death due to severe anemia." (PMID 34359655, 2021). "GATA1 deficiency will lead to abnormal cell apoptosis in the early proliferation and differentiation of erythrocytes, leading to severe anemia and severe thrombocytopenia, and GATA1 plays an indispensable role in determining the fate of bone marrow-erythrocytic lineage during embryogenesis." (PMID 31531120, 2019). "In humans, a severe anemia has been recently described in a family of patients with an inherited splicing mutation of the GATA-1 gene that results in exon skipping and expression of an N-terminally deleted GATA-1 protein (GATA-1s)." (PMID 19513100, 2009).
anemia (continued). "We therefore hypothesize that ribosome haploinsufficiency leads to replication stress and triggers apoptosis in the early self-renewing GATA1− BFU-E C3 subpopulation, and inefficient translation of GATA1 further exacerbates anemia in DBA patients during terminal erythroid differentiation." (PMID 35534476, 2022). "Other relevant findings include the low overall expression of membrane genes and genes involved in erythropoiesis (GATA1, ALAS2, ABCB10, and HEMGN) in CSA and overexpression in the rest of the congenital anemias studied compared to healthy controls." (PMID 39519257, 2024). "Indeed, two GATA1 variants have been reported with an amino acid exchange in position 208, namely G208R and G208S, resulting in severe to moderate macrothrombocytopenia with dyserythropoiesis, respectively with and without anemia." (PMID 36291092, 2022). "Hemolysis and anemia in SCD can initiate an erythropoietin response and stress erythropoiesis, which triggers the expression of the erythropoietin-dependent GATA-1 gene, and in sickle red cell progenitors, an increased generation of miRNA-144." (PMID 34684143, 2021). "As for GATA1, the first evidence for an essential role in erythropoiesis came from the observation that KLF1 knockout mice die in utero around E15 due to fatal anemia." (PMID 30809156, 2019). "The transcription factors Tal1, Gata1, Lmo2 and Fog1 (Zfpm1) all had lower expression in C57BL/6 than BALB/c consistent with more severe anaemia in C57BL/6." (PMID 19365556, 2009). "Together, the GATA1–miR-144/451–GATA2/Myc regulatory axis plays a crucial role in erythropoiesis, and disruption of this pathway can result in impaired red blood cell formation and anemia." (PMID 40650116, 2025). "GATA1-deficient mice result in embryonic lethality due to severe anemia, whereas ΔdblGATA mice lacking the double-GATA enhancer site in the Gata1 promotor region show selective deficiency in eosinophil lineages with only mild anemia." (PMID 38803659, 2024). "The GATA binding protein GATA1 is one of the best studied transcription factors, whose germline defects lead to dyserythropoiesis with or without anemia and variable platelet abnormalities." (PMID 36231035, 2022). "A GATA-1 mutant unable to bind pRb fails to inhibit cell proliferation and results in mouse embryonic lethality by anemia." (PMID 19513100, 2009). "As previously shown, male GATA-1.05/Y mice die in utero from impaired hematopoiesis, whereas heterozygous female mice (GATA-1.05/X) spontaneously recover shortly after birth from embryonic/fetal and neonatal anemia." (PMID 19513100, 2009). "Several transcription factors regulating haematopoiesis, Tal1, Gata1, Zfpm1 and Klf1 were expressed at consistently lower levels in C57BL/6 mice suggesting that these mice have a lower haematopoietic capacity and therefore less ability to recover from haemolysis induced anaemia after infection." (PMID 19365556, 2009). "Decreased affinity of GATA1 for FOG1 has been shown to be caused by the pathogenic missense variants V205M, G208S, and D218G/Y, which are associated with variable dyserythropoiesis (with or without anemia), dysplastic megakaryocytes, and macrothrombocytopenia (OMIM: 300367; 300835)." (PMID 36231035, 2022). "Moreover, HSP70 may play a role in the severe anemia witnessed in individuals with β-Thalassemia (β-TM) since HSP70 directly interacts with free αglobin chains in human β-TM erythroblasts, resulting in HSP70 sequestration in the cytoplasm, a process that promotes GATA-1 degradation." (PMID 39452740, 2024). "We found that PDS increased the proportion of both hematopoietic stem cells and erythroid progenitor cells in the bone marrow, but PPD inhibited spleen erythroid differentiation and reduced the expression of GATA-1 and GATA-2 and could not improve tumor-induced anemia in mice." (PMID 32015754, 2020).